VAV1 (vav guanine nucleotide exchange factor 1)
Diseases named in the same sentence as VAV1 in open-access papers (continued):
Sharing a sentence is not in itself a finding about the gene and the disease.
breast carcinoma (15 papers, 2008 to 2023). "Once established that Vav1 modulates the activation of Akt1 in breast tumor‐derived cells, we investigated the association between the Vav1/p‐Akt (Ser473) levels and the clinical outcome of breast cancer patients." (PMID 29658179, 2018). "This work was aimed to establish the significance of Vav1 expression in breast tumor cells, in terms of tumor progression measured as risk of recurrence in patients with T1-T2, N0, M0 breast cancer." (PMID 24962430, 2014). "Two previous attempts to associate Vav1 with human breast cancer used smaller cohorts of breast cancer specimens and a very small number of human breast cancer cell lines and are less informative and therefore were inconclusive." (PMID 23342133, 2013). "Nek3, while not directly implicated in pre-B cell signaling, phosphorylates Vav1 and 2 in a breast cancer line." (PMID 22693568, 2012). "Interestingly, Vav1 was originally isolated as an in vitro–activated oncogene and has been implicated in breast cancer, pancreatic adenocarcinoma, melanoma, and lung cancer." (PMID 36598812, 2023). "By Spearman analysis, the cytoplasmic level of BPGAP1 positively correlated with Vav1 in breast cancer tissues with an r-score of 0.3909 (P < 0.001)." (PMID 36598812, 2023). "As it is known that, in breast cancer, Akt2 is regulated by various miRNAs, including miR-615 and miR-29b, we explored their possible involvement in the mechanism by which Vav1 affects this Akt isoform." (PMID 35743776, 2022). "We have recently demonstrated that Vav1, ectopically expressed in solid tumors, is capable of down-modulating expression and/or activation of specific Akt isoforms in breast cancer cells." (PMID 32993067, 2020). "Archived formalin‐fixed breast tumor samples allowed to establish the prognostic significance of the Vav1/p‐Akt relationship in patients with early breast cancer." (PMID 29658179, 2018). "Vav1 is expressed in the majority of breast carcinomas, in which we have previously demonstrated its peculiar localization inside the cell nucleus." (PMID 29658179, 2018). "According to its role in modulating nucleic acid metabolism, in mammary tumor cells Vav1 accumulates in subnuclear structures and its downmodulation induces a phenotype‐related expression of genes variously involved in malignant progression." (PMID 29658179, 2018). "Nevertheless, ectopic expression of Vav1 is detected and involved in the pathophysiology of neuroblastoma, pancreatic adenocarcinoma, melanoma, lung and breast cancer." (PMID 25426554, 2015). "On the other hand a role for Vav1 in regulating EMT in breast cancer cannot be excluded, as suggested by the up-regulation of genes whose expression sustains EMT as a consequence of silencing of Vav1." (PMID 24962430, 2014). "Our present study revealed that Vav1 protein expression was observed in some breast cancer cell lines by Western Blot, especially in ER+ cell lines, though with discrepancy in MCF-7 cell line." (PMID 24905577, 2014). "The results indicate that, in early breast cancers patients, high nuclear expression of Vav1 in tumor cells is an independent prognostic factor associated with low risk of distant metastases." (PMID 24962430, 2014). "Concerning breast cancer, Vav1 was reported to be one of the genes with altered expression in medullary breast cancers and a Vav1 transcript higher than in normal tissue was reported in different breast cancer subtypes." (PMID 24962430, 2014).
breast carcinoma (continued). "Contrarily to other solid tumors, in which Vav1 positively correlates with malignancy, the Vav1 transcript in breast cancers seems to be higher in tumors from patients that remained disease free than in patients who developed recurrence." (PMID 24962430, 2014). "Given a positive correlation between Vav1 and ER expression in breast cancer tissue, we were motivated to explore the Vav1 expression along the E2-ER axis." (PMID 24905577, 2014). "It was reported previously that Vav1 was detected in ER-positive breast cancer tissue by immunohistochemistry." (PMID 24905577, 2014). "Vav1 is one of the signalling proteins normally restricted to hematopoietic cells that results ectopically expressed in solid tumors, including breast cancer." (PMID 24962430, 2014). "Herein we aim to investigate the modulation of Vav1 expression in breast cancer cells, and the effect of Vav1 on breast cancer cell proliferation." (PMID 24905577, 2014). "C-Myb affects vav1 transcription in lung cancer cells and is also involved in the E2-ER regulated gene expression in breast cancer cells." (PMID 24905577, 2014). "We not only verified the ectopic expression of Vav1 in human breast cancer cell lines, but also observed that Vav1 expression was induced by 17β-estradiol (E2), a typical estrogen receptor (ER) ligand, in ER-positive cell lines." (PMID 24905577, 2014). "In this study, we aimed to explore the mechanism for Vav1 expression in breast cancer cells in correlation with estrogen-ER pathway." (PMID 24905577, 2014). "Recently, the aberrant expression of Vav1 has been reported and its correlation with estrogen receptor has been addressed in human breast cancer." (PMID 24905577, 2014). "We determined the relative expression levels of Vav1 in a series of 50 breast cancer cell lines using data from a gene expression profiling study." (PMID 23342133, 2013). "Based on published gene profiling of 50 breast cancer cell lines, several Vav1-expressing cell lines were identified." (PMID 23342133, 2013). "The fact that Vav1 is shown by us in this study to have opposite effects when expressed in two breast cancer cell lines, MCF-7 and AU565, clearly highlights the importance of the cellular environment on Vav1 function." (PMID 23342133, 2013). "Immunohistochemical analysis of primary human breast carcinomas indicated that Vav1 is expressed in 62% of 65 tumors tested and is correlated positively with estrogen receptor expression." (PMID 23342133, 2013). "Based on our results, Vav1 can be included in the existing gene profiles, especially in light of its unexpected expression in a breast cancer cell line such as MCF-7 following treatment with estradiol; however its prognostic value remains to be determined." (PMID 23342133, 2013). "Vav1 is found to be expressed in a large proportion of human breast tumors illustrating its potential huge importance in breast cancer biology." (PMID 23342133, 2013). "It is possible that in several of the breast cancer cell lines cbl-c expression is elevated, leading to Vav1 ubiquitination." (PMID 23342133, 2013). "In this study, we analyzed the expression and function of Vav1 in human breast tumors and breast cancer cell lines." (PMID 23342133, 2013). "In this study, we show that Vav1 is expressed in the majority of breast carcinomas and that its ectopic expression in breast cancer cell lines can induce significant changes in these cells, causing either transformation or cell death." (PMID 23342133, 2013). "To increase our understanding of Vav1 activity and regulation in human cancers, we analyzed the involvement of Vav1 in human breast cancer." (PMID 23342133, 2013). "Furthermore, VAV1 expression correlated with estrogen receptor expression was noted in 42% (40/65) of primary human breast cancers." (PMID 37174676, 2023).
breast carcinoma (continued). "Based on the need of precise isoform-specific inhibitors, especially in the treatment of the most aggressive breast cancers, the role of Vav1 as a potential down-regulator of individual Akt isozymes was investigated in the MDA-MB-231 cell line, highly invasive and with a triple negative phenotype." (PMID 35743776, 2022). "Silencing of Vav1 resulted in the increased expression in Akt1 in ER+ cells and in the up-modulation of Akt2 in ER- breast tumor cells, including those with a triple negative phenotype, still representing the most aggressive breast cancer." (PMID 35743776, 2022). "As the use of specific or pan Akt inhibitors may not be sufficient or may even be detrimental, increasing the levels of Vav1 could be a new approach to improve breast cancer outcomes." (PMID 29658179, 2018). "The relationship between cellular staining of Vav1 and activated Akt was also investigated in the tumor tissue of 126 patients with completely resected (T1‐T2, N0) breast cancer, showing that more than 80% of tumors expressing high levels of Vav1 displayed low levels of phosphorylated Akt." (PMID 29658179, 2018). "This work was aimed to establish whether Vav1 has a role in modulating the Akt signaling in breast cancer cell lines belonging to different tumor phenotypes." (PMID 29658179, 2018). "They include Akt1 and the gene encoding for the PI3K/Akt activator PDGFRB, suggesting that Vav1 may affect the Akt‐related machinery in mammary tumors." (PMID 29658179, 2018). "In this study, we observed that the aberrant expression of Vav1 correlated well with the production of Cyclin D1, a critical mediator of estrogen-stimulated cell cycle progression, thus contributing to the proliferation of breast cancer cells." (PMID 24905577, 2014). "Immunochemical analysis with the anti-Vav1 antibody was performed on 5 breast cancer-derived cell lines (BT-474, MCF7, MDA-MB-453, MDA-MB-468 and MDA-MB-231) with different morphology, immunoprofile and invasive properties, representing the most frequent subtypes of breast tumors." (PMID 24962430, 2014). "Our data suggested that estrogen may promote breast cancer cell growth partially by triggering the aberrant expression of Vav1." (PMID 24905577, 2014). "If we consider that a breast cancer patient has very good chances of a disease-free survival if the cancer is treated early, the monitoring of Vav1 in early breast tumors may be beneficial in selecting the more appropriate therapy." (PMID 24962430, 2014). "This suggests that, inside the nucleus of breast tumor cells, Vav1 may compete with the classical nuclear activity of ERα, a ligand-dependent transcription factor known to play a crucial role in breast cancer development and/or progression." (PMID 24962430, 2014). "Roles in breast cancer of proteins codified by genes whose expression is regulated by Vav1." (PMID 24962430, 2014). "Nevertheless, Vav1 was aberrantly expressed in breast cancer tissue and cell lines." (PMID 24905577, 2014). "Finally, we showed that the amount of Vav1 expression correlated with the expression of Cyclin D1 and influenced the cell cycle progression in breast cancer cells." (PMID 24905577, 2014). "In breast tumors, contrarily to Vav2 and Vav3, that play synergistic roles in breast cancer by sustaining tumor growth, neo-angiogenesis and metastasis, the Vav1 transcript seems to be higher in tumors from patients that remained disease free than in patients who developed recurrence." (PMID 24962430, 2014).
breast carcinoma (continued). "Since the high heterogeneity of breast tumors makes difficult to predict the evolution of early breast neoplasias, the evaluation of nuclear Vav1 levels may help in the characterization and management of early breast cancer patients." (PMID 24962430, 2014). "This study emphasized the involvement of Vav1 ectopic expression in ER positive breast cancer cells, which reinforced the hypothesis that Vav1 could exert its oncogenic role in human breast cancer." (PMID 24905577, 2014). "In particular, Vav1 may serve as a prognostic biomarker and a target for new therapies aimed to prevent breast cancer progression." (PMID 24962430, 2014). "To overcome this hurdle for studying the functional role of Vav1 in human breast cancer, we overexpressed Vav1 in two breast cancer cell lines, AU565 and MCF-7, achieving Vav1 protein levels which on immunohistochemical assay are similar to those present in primary human tumors." (PMID 23342133, 2013). "To study whether ectopically expressed Vav1 in breast cancer cells is functionally active, we stimulated MCF-7Vector and MCF-7Vav1 cells with EGF and AU565Vector and AU565Vav1 with CSF1 for various time intervals." (PMID 23342133, 2013). "To elucidate whether modulation of the complex pathways triggered by Akt may be at the basis of the role of Vav1 in breast cancer cells, we explored here the ability of this protein to affect Akt expression and/or activation in breast tumor cells with different phenotypes." (PMID 29658179, 2018). "As in breast cancer, the use of specific or pan Akt inhibitors may not be sufficient or may even be detrimental as it might promote tumor invasiveness and cancer dissemination, protocols devised to increase the levels of Vav1 could be an option to improve breast cancer outcomes." (PMID 29658179, 2018). "The E2-induced Vav1 level in breast cancer cells was in favor of promoting Cyclin D1 expression and accelerating the cell proliferation, and Vav1 might partially contribute to the pathogenesis and prognosis of breast cancer." (PMID 24905577, 2014). "For example, the demethylation of the vav1 gene promoter is detected in primary pancreatic adenocarcinomas; methylation of CpG in 5′-regulatory sequences of the vav1 promoter is addressed in lung cancer cells; and degradation of Vav1 through Cbl ubiquitination is proposed in breast cancer cells." (PMID 24905577, 2014). "The non-hematopoietic expression of Vav1 has been reported recently in association with several human malignancies, including pancreatic ductal adenocarcinomas, lung cancer, neuroblastoma, melanoma, and breast cancer." (PMID 24905577, 2014). "Vav1 showed the highest expression in patients who remained disease free (0.89 ± 0.48) with much lower expression in those patients with metastatic disease (0.01 ± 0.003); with local recurrence (0.02 ± 0.012) and in patients who died from breast cancer (0.03 ± 0.016)." (PMID 18925966, 2008). "Accordingly, EHop-016 blocked the interaction between Vav1/2 and Rac with an IC50 of ∼1 μM in metastatic breast cancer cells." (PMID 32322580, 2020). "Although the oncogenic form of Vav1 identified in the screen has not been detected in clinical human tumors, its wild-type form has recently been implicated in mammalian malignancies, including neuroblastoma, melanoma, pancreatic, lung and breast cancers, and B-cell chronic lymphocytic leukemia." (PMID 26353933, 2015). "Since Vav1 activates Rac1 in immune cells, we examined Rac1-GTP activation in the Vav1-expressing breast cancer cell lines." (PMID 23342133, 2013). "Here we have reported an immunohistochemical analysis of Vav1 expression in 137 primary node negative early breast cancers representing all the most frequent breast tumor histotypes." (PMID 24962430, 2014). "Here we examined the expression of Vav1 in human breast cancer cell lines, using Vav1 abundant Jurkat cells as positive control and its derived vav1-null cells (J.Vav1) as negative control (left two lanes)." (PMID 24905577, 2014).
breast carcinoma (continued). "In recent years, aberrant expression of Vav1 has been reported in non-hematopoietic cancers including human breast cancer." (PMID 24905577, 2014). "Accordingly, we find mRNA expression of Vav1 is many breast cancer cell lines; surprisingly we find little or no Vav1 protein mainly due to degradation by Cbl-c." (PMID 23342133, 2013). "Therefore, in breast cancer tissues, Trio levels, but not Tiam1 or Vav1, were high and correlated with a poor outcome." (PMID 32322580, 2020). "The subcellular localization of Vav1 was also investigated in 5 human breast tumor-derived cell lines (BT-474, MCF7, MDA-MB-453, MDA-MB-468 and MDA-MB-231) representing the most frequent subtypes of breast cancer in terms of immunoprofile, molecular phenotype and in vivo tumorigenicity." (PMID 24962430, 2014). "Although loss of E-cadherin in human breast cancer may not be causal for EMT and even not a necessity, these data indicate that the effects of Vav1 on metastatic potential of breast tumor cells are not mediated by this junction protein." (PMID 24962430, 2014).